RPP38 (ribonuclease P/MRP subunit p38)
Description:
Component of ribonuclease P, a ribonucleoprotein complex that generates mature tRNA molecules by cleaving their 5'-ends. Also a component of the MRP ribonuclease complex, which cleaves pre-rRNA sequences.
Tractability: PROTAC: ubiquitination databases record sites on it; its protein half-life has been measured.
Gene: Protein-coding gene on chromosome 10 (15,097,120 to 15,139,818, forward strand). Ensembl gene ENSG00000152464.
Subcellular location: Nucleus, nucleolus
Subcellular location (Human Protein Atlas): Nucleoli
Pathways (Reactome):
Metabolism of RNA: Major pathway of rRNA processing in the nucleolus and cytosol; tRNA processing in the nucleus
Gene Ontology:
Molecular function: protein binding; ribonuclease P activity; ribonuclease P RNA binding
Biological process: tRNA 5'-leader removal; RNA processing
Cellular component: multimeric ribonuclease P complex; nucleolar ribonuclease P complex; nucleolus; ribonuclease MRP complex; nucleoplasm; nucleus
Genetic constraint (gnomAD): Loss-of-function variants: 3 observed, 2.56 expected, observed/expected ratio (o/e) 1.17, 90% interval 0.49 to 1.9. That is too few expected variants to judge how well the gene tolerates losing a copy. Missense variants: 358 observed, 356.54 expected, observed/expected ratio (o/e) 1, 90% interval 0.92 to 1.1. Synonymous variants: 151 observed, 138.73 expected, observed/expected ratio (o/e) 1.09, 90% interval 0.95 to 1.25.
Homologues: Orthologues: chimpanzee RPP38 (99% identical), macaque RPP38 (93% identical), guinea pig RPP38 (77% identical), mouse Rpp38 (76% identical), dog RPP38 (75% identical), pig RPP38 (72% identical), rat Rpp38 (72% identical), tropical clawed frog rpp38 (47% identical), zebrafish rpp38 (42% identical).
Diseases named in the same sentence as RPP38 in open-access papers:
RPP38 is named in the same sentence as 3 diseases in open-access papers, as found by Europe PMC text mining. Sharing a sentence is not in itself a finding about the gene and the disease.
RPP38 shares sentences with these, for which no sentence is quoted: pulmonary arterial hypertension (1 paper); systemic lupus erythematosus (1); type 1 diabetes (1).